IRF3 (interferon regulatory factor 3)
Diseases named in the same sentence as IRF3 in open-access papers (continued):
Sharing a sentence is not in itself a finding about the gene and the disease.
infection (continued). "For example, after infection with IAV, mPGES‐1 deficient macrophages exhibit an early increase in phospho‐IRF3, compared to wild‐type (WT) macrophages, augmented type I IFN, and decreased viral load, which was drastically inhibited by addition of exogenous PGE2." (PMID 32700336, 2020). "Furthermore, carvedilol increased the phosphorylation of TBK1, IRF3, IRF7, and STING and the dimerization and translocation of IRF3 after the infection." (PMID 33243993, 2020). "After infection with a related strain, Mengovirus, however, IRF3 still localized to the nucleus." (PMID 32645843, 2020). "Focusing on earlier time points, before loss of IFN production/signaling becomes the overwhelming factor affecting infection efficiency, may reveal more subtle differences conferred by abrogation of either IRF3 or STAT1 signaling." (PMID 31921100, 2019). "However, IFI204 can only enhance the transcription of Ifnb induced by the infection of HSV-1 in the presence of IRF3 as previously reported." (PMID 31603949, 2019). "In addition, ectopic expression of MDA5 or RIG-I enhances the activation of the IFN-β mRNA and IRF3 phosphorylation upon EV-A71 infection." (PMID 31787104, 2019). "Compared to control and siRNA groups, more IRF3 migrated into the nucleus during infection." (PMID 30791397, 2019). "After s.c. infection with CHIKV Irf3/7 double deficient mice succumb to the virus while 100% of pDC:Irf7+ mice survive the infection exhibiting no overt clinical symptoms similar to WT mice." (PMID 31031767, 2019). "Infection in conditions of unfolded protein response priming leads to early activation of innate antiviral responses and cell intrinsic inhibition of viral replication, which is interferon regulatory factor 3 dependent." (PMID 31467282, 2019). "Infection of NH/P68 phosphorylates IRF3 and induces its binding to chromatin." (PMID 30918080, 2019). "In addition, phosphorylation of MITA, TBK1, and IRF3 was increased following infection with HCMV-ΔUL42 compared to wild-type HCMV." (PMID 31107917, 2019). "However, at later times of infection (24–48 h) the expression of IRF3 returned back to basal levels and the expression of STAT2 was clearly enhanced." (PMID 31673117, 2019). "This indicates that both NF-κB and IRF3 are activated by hMPV infection." (PMID 29343779, 2018). "However, TBK1_tv1 and TBK1_tv2 also significantly inhibited the IFNφ1 and/or IFNφ3 promoter activity induced by RIG-I, MAVS, and IRF3 in response to SVCV infection." (PMID 29441066, 2018). "The authors suggested that IL-1β produced by activated microglia may trigger IRF3 activity in astrocytes to amplify innate immune responses and provide a second line of defense against infection in the CNS." (PMID 29559569, 2018). "We next determined activation and phosphorylation of IRF-3 at early time points after infection." (PMID 30496325, 2018). "Previous microarray analyses have indicated that during the infection and replication of various viruses, the genes induced in the antiviral responses include those that are involved in the activation of NF-κB and IRF-3." (PMID 29368634, 2018). "The mechanism by which IRF3-dependent necrosis is induced during infection is unknown, though the transcriptional activity of IRF3 itself is not necessary to elicit death." (PMID 29324702, 2018). "However, it is based on the translocation of the transcription factor IRF3 in response to infection, thus requiring a careful selection of cell lines according to the virus of interest." (PMID 29543803, 2018). "To examine whether miR-199a can affect the TBK1-dependent pathway, we used western blotting to monitor the protein expression of TBK1, p-TBK1, IRF3, and p-IRF3 in J774a.1 cells a t 24 or 48 h post-infection." (PMID 30042930, 2018). "TBK1 and IRF3 were phosphorylated, along the time course of infection." (PMID 28102839, 2017). "Indeed, the γ134.5 mutant sequentially induced phosphorylation of IRF3 and RelA/p65 at 3 h post infection of DCs." (PMID 28150813, 2017).
infection (continued). "IRF3 showed significantly decreased expression at the acute stage of infection (logFC = −7.07), with similarly low expression levels until the chronic stage of infection." (PMID 28487699, 2017). "We found that phosphorylation of IRF3 was decreased in cells infected with the CA/04-NAK331N and CA/04-NAS79L,K331N variants compared to cells infected with the CA/04 or CA/04-NAS79L viruses at 16 h post-infection." (PMID 28750037, 2017). "Furthermore, the relative concentrations of IRF3 clearly increased in the nucleus and reduced in the cytoplasm of infected J774A.1 cells at 4 and 24 h-post-infection." (PMID 28529930, 2017). "The infection efficiency of the IRF3 shRNA-carrying adenovirus in the KCs reached 100%." (PMID 27448985, 2016). "Furthermore, different modes of IRF3 activation allow cells to respond accordingly to the severity of infection." (PMID 27809273, 2016). "Upon infection with viral DNA or RNA, TRIM9 short isoform undergoes Lys-63-linked auto-polyubiquitination and recruits GSK3β to TBK1, resulting in the activation of the IRF3 signaling pathway." (PMID 27667714, 2016). "Subsequently, we examined IRF3 phosphorylation during the course of HP-PRRSV infection." (PMID 27329948, 2016). "After infection, phosphorylated and dimerized IRF3 is captured by the nuclear CBP/p300 proteins." (PMID 27835978, 2016). "Additionally, 33°C is lowerthan 37°C, and A549 cells showed defective IRF3 activation, even thoughHPeV1 was produced at 33°C incubation, which suggested the low host response tovirus infection at 33°C." (PMID 25646764, 2015). "In order to analyze the magnitude of the IFN response, levels of IFN-β mRNA were quantified by qRT-PCR, and subcellular localization of IRF3 was examined by immunofluorescence during the course of infection at a MOI of 1, which results in more than 90% of infected cells as measured by IF." (PMID 25837699, 2015). "Similarly, enterovirus 68 infection inhibits the ability of HeLa cells to respond to poly(I:C) and this is associated with cleavage of TICAM-1 and reduced IRF-3 activation." (PMID 26437794, 2015). "This may reflect a requirement to maintain a basal level of ISG expression in order to give a rapid antiviral response in the initial stages of infection, though NF-κB has been shown to be more important than IRF3 for this." (PMID 25733689, 2015). "Indeed, it has been reported that MTB induces IFN production during macrophage infection via the activation of a STING/TBK1/IRF3 signaling axis." (PMID 26654095, 2015). "Particularly, it has been reported that wtRSV infection of A546 cells induces activation and nuclear localization of IRF3; however, detection of this transcription factor is dramatically diminished with the onset of NS1/NS2 expression, due mainly to protein degradation." (PMID 26501312, 2015). "However, overexpression of TRIM21 prior to infection resulted in a reduction of p-IRF3 levels post infection compared to the CHME3 cells only infected with JEV without TRIM21 transfection." (PMID 24485101, 2014). "IMPORTANCE Although the pestivirus N-terminal protease, Npro, has been shown to have an important role in degrading IRF3 to prevent apoptosis and interferon production during infection, the function of this unique viral protease in the pestivirus life cycle remains to be elucidated." (PMID 24965446, 2014). "Interestingly, IFN produced by PMLIV-expressing cells upon VSV infection was due to activated IRF3, since a higher amount of phosphorylated IRF3 (P-IRF3) was detected 6 h post-infection of cells expressing PMLIV compared to control cells." (PMID 24586174, 2014). "Taken together, analysis of the characteristic cellular responses to infection revealed that although high levels of TLR3 expression increased IRF3 phosphorylation in response to WNV infection at late times, the TLR3 status did not affect infectivity, viral genome replication or WNV-induced CPE." (PMID 25127040, 2014).
infection (continued). "Following infection in the presence of ActD, however, the level of nuclear translocation for both IRF3 and p65 dropped to around 1% for both viruses, indicating that ActD efficiently inhibits activation and subsequent nuclear translocation of both of these transcription factors." (PMID 24478437, 2014). "Thus, the very weak activation of IRF3 during wt infections is most likely due to NS1 inhibiting activation of the IFN induction cascade." (PMID 24478437, 2014). "Similarly, after infection of IRF3−/−/7−/− MEFs with WT virus, 1639 and 1665 transcripts were upregulated and down regulated, respectively." (PMID 25375107, 2014). "Unlike PMLIII, whose anti-VSV activity is IFN-independent, PMLIV can act at two stages: it confers viral resistance directly in an IFN-independent manner and also specifically enhances IFN-β production via a higher activation of IRF3, thus protecting yet uninfected cells from oncoming infection." (PMID 24586174, 2014). "Furthermore, increasing the multiplicity of infection for PR8-ΔNS1 considerably increased the levels of IRF3 activation in the presence of CHX relative to the amount in untreated infected cells (data not shown)." (PMID 24478437, 2014). "The results above indicate that infection with CSFV induces IRF-3 activation in PAMs." (PMID 24034559, 2013). "In contrast to infection with wt rotaviruses, infection with mutant rotaviruses encoding C-terminally truncated NSP1 proteins fails to induce IRF3 degradation." (PMID 23359266, 2013). "We found that EV71 infection suppresses total IRF3 expression at the late stage of infection." (PMID 23650567, 2013). "The new-emerging and most pathogenic CoV, severe acute respiratory syndrome coronavirus (SARS-CoV) inhibits the induction of IFN-β through blocking translocation of the transcription factor interferon regulatory factor 3 (IRF-3) from the cytoplasm to the nucleus at a later time point in infection." (PMID 22312431, 2012). "Increased levels of NP at later times during infection may efficiently inhibit the RIG-I/IRF3 pathway, thus enabling virus to down-regulate the type I IFN response." (PMID 22629479, 2012). "In striking contrast, however, Irf3−/− mice produced significantly higher levels of pro-inflammatory cytokines in the serum on day 3 post-infection compared to wild type, whereas IL-17, IL-5 and MIP-1α were not detectably different between the strains (data not shown)." (PMID 22911267, 2012). "Low levels of activated IRF3 could be detected in all virus-infected T cells 48 hr after infection, contrary to a recent study that suggested IRF3 itself is degraded by Vpu." (PMID 23159053, 2012). "However, significant degradation of IRF3 was also observed at 24 hours after infection, and as a result, the expression of the IFNβ gene was still turned-off." (PMID 21677781, 2011). "As previously shown, IRF3 undergoes virus-induced degradation, and after 24 hrs infection, relatively little IRF3 protein could be detected." (PMID 21677781, 2011). "Intriguing enough, although overexpressed IRF3 could recruit TBK1 (top panel lane 2), infection with MHV-A59 led to enhanced association of endogenous TBK1 with the complex (top panel lane 4)." (PMID 21364999, 2011). "Hence, infection with the mutant virus unable to express the viral kinase ORF47p results in the restoration of IRF3 serine 396 phosphorylation, homodimerization and an enhanced expression of IRF3 target genes such as IFN-β and ISG15." (PMID 21347389, 2011). "IRF-3 is therefore required for the full induction of apoptosis by infection with MVA/MVAΔF1L." (PMID 21698224, 2011). "Therefore a tripartite complex containing TBK1/IRF3/PLP2 would exist in cells after infection of MHV-A59." (PMID 21364999, 2011). "Furthermore, the transient induction of IRF3 following infection with WT HSV-1 is insufficient to promote accumulation of ISG56 protein." (PMID 20454685, 2010).
infection (continued). "We failed to observe degradation of any known components of the IRF3 pathway following WT infection, either in this study or a previous report, suggesting that proteasome function may be indirect." (PMID 20454685, 2010). "The results suggest that IFNβ is activated by infection and that IFNβ might be an essential effector molecule in IRF3-dependent bacterial clearance." (PMID 20886096, 2010). "However, during the course of infection ICP0 inhibits IRF3 phosphorylation, dimerization and nuclear translocation when localized in the cytoplasm but has no apparent inhibitory activity when located within the nucleus." (PMID 20454685, 2010). "Infection with SeV served as a positive control for IRF3 activation and ISG56 induction." (PMID 20454685, 2010). "Many viruses induce activation of IRF-3 within 3–6 h post-infection." (PMID 21994652, 2010). "Moreover, ISG56, another IRF-3 target gene, was induced late during infection and to lower levels as compared to ISG54 and ISG49 in wild type, infected DCs." (PMID 20140199, 2010). "Infection of Caco-2 cells with SA11-4F reduced IRF3 to levels that were nearly undetectable." (PMID 21994581, 2009). "Moreover, there are no reports of any PRR that play an important role in activation of IRF3/NF-κB during HPIV3 infection." (PMID 19922606, 2009). "Moreover, RIGI was involved in activating both arms (NFκB/TNFα and IRF3/IFNα/β) of innate immunity following HPIV3 infection." (PMID 19922606, 2009). "Some of this disparity could reflect direct IRF-3-dependent antiviral responses in specific cell types to control infection." (PMID 17676997, 2007). "IRF-3−/− mice also averaged significantly higher viral titers than wild-type mice in the brain on days 6, 8, and 10 after infection (20-fold, p < 0.0001; ∼200-fold, p < 0.0001; and 10-fold, p < 0.005, respectively), which corresponded with increased morbidity and mortality." (PMID 17676997, 2007). "Increased WNV replication was observed in IRF-3−/− macrophages beginning at 24 h after infection." (PMID 17676997, 2007). "IRF-3−/− mice are more susceptible to encephalomyocarditis virus (EMCV), and IRF-3−/− MEFs exhibited a reduced capacity to produce IFN after infection with several RNA and DNA viruses, including Newcastle disease virus, herpes simplex virus (HSV), vesicular stomatitis virus (VSV), and EMCV." (PMID 17676997, 2007). "Thus, a deficiency of IRF-3 in vivo had a small and transient effect on early IFN gene induction in lymphoid tissues after infection with WNV." (PMID 17676997, 2007). "As a deficiency of IRF-3 in macrophages ex vivo significantly altered basal expression of key host defense molecules, the expanded in vivo tropism in IRF-3−/− mice may be due, in part, to enhanced infection in normally resistant tissue macrophages." (PMID 17676997, 2007). "Importantly, we also monitored the assembly of IR-HCTFBSs across the coordinates obtained from HeLa, in lung A549 cells and B-lymphocytes NM, and identified ∼240 and ∼190 common instances, respectively, that are bound by IRF3 6h upon virus-infection according to our IRF3-ChIP-seq assays." (PMID 40131776, 2025). "Similarly, IRF-3 mRNA levels experienced a significant reduction post-TLR3 silencing at all time points following H9N2 AIV infection (p < 0.005), aligning with the trends observed for NF-κB and highlighting the interconnected regulatory mechanisms governing IRF-3 expression." (PMID 38731436, 2024). "IRF3 is a transcription factor essential for innate immunity against viruses, and its protein levels and activity can be precisely regulated by post-translational modifications to effectively protect the host from infection and prevent excessive immune pathology." (PMID 38739631, 2024).
infection (continued). "In addition, Western blot results showed that compared with control cells, in 293T cell line knockout of HDAC8 significantly reduced the protein expression of RIG-I, MAVS, p-TBK1 and p-IRF3 during VSV-GFP infection, which are key regulators of RLRs signaling pathway and subsequent immune response." (PMID 39035358, 2024). "We speculated that the reason for this might be that a cytosolic DNA sensor, cGAS, competed in order for the substrate ATP to produce more cyclic-GMP-AMP (cGAMP), which binds to and activates the adaptor protein STING, resulting in IRF3 activation and IFNβ induction at the late stage of infection." (PMID 39205282, 2024). "However, we do not provide sufficient evidence to suggest that zebrafish mylipb could also reduce the dimerization and nuclear translocation of irf3 after infection with SVCV." (PMID 38739631, 2024). "Moreover, increased IRF3 nuclear translocation was evident after Alpha ΔOrf6 infection at 24 h.p.i." (PMID 38228858, 2024). "Furthermore, unlike the mRNA results, the PRRSV infection increased the level of phosphorylation of IRF3, which may be related to the cell’s own immunity against infection." (PMID 38005850, 2023). "In addition, confocal experiments also showed that MORC3 and IRF3 are located in the nucleus under SCRV infection, suggesting that they may be related." (PMID 38150467, 2023). "However, in presence of VLPs-M8 this induction correlated with the block of viral replication, as evidenced by the reduced expression of viral products, demonstrating that VLPs-M8 elicited a strong IRF3-dependent antiviral response that limited infection progression." (PMID 36590581, 2022). "With this in mind, it would be interesting to see whether Myotis davidii would be more susceptible to SARS-CoV-2, and if IRF3 and NLRP12 levels are affected during infection, or if the unique features implicated in chiopteran tolerance for multiple viruses would still protect this species." (PMID 33372854, 2021). "Therefore, we hypothesized that T. gondii may take advantage of this interaction between PI3K/AKT signalling and TBK1/IRF3 pathway while its infection period." (PMID 34464509, 2021). "UBE3C was shown to regulate WT and phosphorylation deficient IRF3 and IRF7 levels in homeostatic conditions, as well as during infection, suggesting that it might target the IRFs during steady state conditions as a part of protein QC, and independently of their activation." (PMID 33808506, 2021). "In addition, phosphorylation of IRF3 after infection of mouse cancer cell lines was also evaluated." (PMID 34553028, 2021). "Western blotting analysis also showed that infection with the Fin-25 strain induced phosphorylation of interferon regulatory factor 3 (IRF3) and p38 in Calu-3 cells starting from 48 h p.i., while the infection with the Fin-1 virus induced very weak phosphorylation of p38 and IRF3 at 72 h p.i.." (PMID 34378952, 2021). "Thus, although loss of IRF3 transcription does not render mice permissive for infection, it does result in reduced virus control in mice lacking the type I IFN receptor." (PMID 34591933, 2021). "Thus, it was possible that PRRSV induced the production of IFN-α in porcine AMs, maybe by activating IRF3 phosphorylation at the early phase of infection." (PMID 32046249, 2020). "However, GLRX removes this modification after infection and thus supports IRF3 activity." (PMID 32645843, 2020). "We found that upon JSY13 and ΔUL13 mutant infection, IRF3 nuclear translocation could occurred." (PMID 32933581, 2020). "However, although infection with bRSV induced similar levels of IRF3 nuclear translocation (bottom right), significantly, the NF-κB subunit p65 remained cytoplasmic, coalescing into intracytoplasmic puncta, mostly perinuclear, and present only in infected cells (bottom left)." (PMID 32878896, 2020).